SEPTIN5 (septin 5)
Description:
Filament-forming cytoskeletal GTPase (By similarity). May play a role in cytokinesis (Potential). May play a role in platelet secretion (By similarity).
Synonyms: CDCrel-1; PNUTL1; SEPT5; HCDCREL-1; H5; Septin-5; CDCREL; CDCREL1
Tractability: Antibody: its Gene Ontology location is reachable by antibodies, with high confidence. PROTAC: ubiquitination databases record sites on it.
Gene: Protein-coding gene on chromosome 22 (19,714,467 to 19,724,224, forward strand). Ensembl gene ENSG00000184702.
Subcellular location: Cytoplasm; Cytoplasm, cytoskeleton
Subcellular location (Human Protein Atlas): Actin filaments; Cytosol; Nucleoplasm
Gene Ontology:
Molecular function: identical protein binding; protein binding; GTPase activity; molecular adaptor activity; structural molecule activity; GTP binding
Biological process: regulation of exocytosis; adult behavior; cytoskeleton-dependent cytokinesis; intracellular protein localization; regulation of synaptic vesicle exocytosis; social behavior
Cellular component: plasma membrane; synaptic vesicle; cell division site; microtubule cytoskeleton; septin complex; septin ring; cytoplasm; cytoskeleton
Genetic constraint (gnomAD): Loss-of-function variants: 16 observed, 49.67 expected, observed/expected ratio (o/e) 0.32, 90% interval 0.22 to 0.49. The upper end of that interval is the gene's LOEUF score, 0.49, which puts it in group 2 of 6, group 1 being the genes least tolerant of losing a copy. Missense variants: 376 observed, 506.55 expected, observed/expected ratio (o/e) 0.74, 90% interval 0.68 to 0.81. Synonymous variants: 208 observed, 196.94 expected, observed/expected ratio (o/e) 1.06, 90% interval 0.94 to 1.18.
Homologues: Orthologues: macaque SEPTIN5 (100% identical), mouse Septin5 (99% identical), rat Septin5 (99% identical), chimpanzee SEPTIN5 (96% identical), pig SEPTIN5 (96% identical), dog SEPTIN5 (95% identical), guinea pig SEPTIN5 (95% identical), zebrafish septin5b (85% identical), zebrafish septin5a (83% identical), Drosophila melanogaster Septin2 (38% identical), Caenorhabditis elegans unc-61 (36% identical). Paralogues in human: SEPTIN1 (62% identical), SEPTIN2 (56% identical), SEPTIN7 (52% identical), SEPTIN3 (42% identical), SEPTIN9 (41% identical), SEPTIN6 (40% identical), SEPTIN8 (40% identical), SEPTIN10 (39% identical), SEPTIN11 (39% identical), SEPTIN14 (39% identical), SEPTIN12 (38% identical), TMEM250 (9% identical).
Diseases named in the same sentence as SEPTIN5 in open-access papers:
SEPTIN5 is named in the same sentence as 49 diseases in open-access papers, as found by Europe PMC text mining. Sharing a sentence is not in itself a finding about the gene and the disease. The quoted sentences say what the papers report.
Parkinson disease (12 papers, 2011 to 2020). A progressive degenerative disorder of the central nervous system characterized by loss of dopamine producing neurons in the substantia nigra and the presence of Lewy bodies in the substantia nigra and locus coeruleus. "In addition to AD, previous studies have linked SEPTIN5 to Parkinson’s disease (PD), demonstrating that it accumulated in dopaminergic neurons due to parkin dysfunction, resulting in neurotoxicity." (PMID 33203136, 2020). "Interestingly, one of the identified genes, Septin5, participated in pathogenic process of Parkinson's disease which also developed encephalitis and CNS dysfunction as well." (PMID 22361110, 2012). "Septin 3 and 5 are both down-regulated in pR5, with Septin 5 accumulating in Parkinson's disease (PD) brain." (PMID 22558197, 2012). "Interestingly, Septin 5, one of the genes isolated from HPAI H5N1-infected brain tissues has been reported to participate in the pathogenic process of Parkinson's disease." (PMID 22361110, 2012). "The four candidate genes are ubiquitin B (UBB), septin 5 (SEPT5), G protein-coupled receptor 37 (GPR37) and Tyrosine hydroxylase (TH), all of which have been involved in the Parkinson disease pathway." (PMID 21731658, 2011).
schizophrenia (6 papers, 2008 to 2025). A major psychotic disorder characterized by abnormalities in the perception or expression of reality. "Septin 5 gene is deleted in velocardiofacial syndrome (22q11.2 deletion syndrome), implicated significantly in both autism and schizophrenia." (PMID 40779003, 2025).
Anxiety (3 papers, 2012 to 2025). Intense feelings of nervousness, tension, or panic often arise in response to interpersonal stresses. "In the same cohort, light/dark transition test data were comparable between Septin5+/+ and Septin5−/− mice, indicating that baseline anxiety-like behavior, as assessed by this test, was similar in both Septin5+/+ and Septin5−/− mice." (PMID 41225651, 2025).
cerebellar ataxia (3 papers, 2021 to 2023). A neurological syndrome characterized by clumsy and uncoordinated movement of the limbs, trunk, and cranial muscles. "Previously, autoantibodies against another neuron-specific septin, septin-5, have been reported in patients with cerebellar ataxia, which was associated with eye movement disorders in most of them." (PMID 36997937, 2023). "Septin proteins as target antigens in neurological autoimmune diseases were first described in patients with cerebellar ataxia and anti-septin-5 autoantibodies." (PMID 36997937, 2023). "Autoantibodies against septin-5 are associated with non-paraneoplastic cerebellar ataxia, and autoantibodies against septin-7 with encephalopathy with prominent neuropsychiatric features." (PMID 36997937, 2023).
autism (2 papers, 2021 to 2025). Persistent deficits in social interaction and communication and interaction as well as a markedly restricted repertoire of activity and interest as well as repetitive patterns of behavior. "Septin 5 gene has been associated with affective behaviors, cognition and social interaction functions, exemplified in cerebellar involvement in autism." (PMID 40779003, 2025). "Both changes in ERK activity and expression of presynaptic proteins such as synapsin-2 and septin-5, have been linked with social interaction and autism-like behaviors, providing a possible pathway connecting system xc− deficiency with phenotypes which we observed in vivo." (PMID 32366950, 2021).
encephalitis (2 papers, 2012 to 2023). An acute inflammatory process affecting the brain parenchyma. "Psychiatric symptoms can be observed in anti septin-5 encephalitis." (PMID 37435157, 2023).
Autoimmunity (1 paper, 2023). The occurrence of an immune reaction against the organism's own cells or tissues. "Altogether, the different clinical phenotypes reported in patients with anti-septin-3, anti-septin-5 or anti-septin-7 autoimmunity so far suggest that these autoantibodies may be markers for different clinical presentations." (PMID 36997937, 2023).
cutaneous melanoma (1 paper, 2024). A primary melanoma arising from atypical melanocytes in the skin. "Other than MTAP and SEPTIN5, CDKN2A, CDKN2B, HIRA, and DGCR8 were the only recurrently altered cutaneous melanoma genes that were not recurrently altered in acral or mucosal melanomas, which frequently lack the presence of UV-induced mutations." (PMID 38758740, 2024).
neuroblastoma (1 paper, 2020). Neuroblastoma (NB) is the most common solid, extracranial childhood tumor. "SEPTIN5 was found to colocalize with GFP-LC3-positive autophagosomal vesicles in neuroblastoma cells." (PMID 33203136, 2020). "However, the reduction in BACE1 levels was only detected in homozygous but not in heterozygous Septin5 knockout mice or after the downregulation of SEPTIN5 in neuroblastoma or cultured primary mouse cortical cells, suggesting that a complete loss of Septin5 was needed for this effect." (PMID 33203136, 2020). "This suggests that SEPTIN5 may additionally affect the trafficking of APP through the secretory pathway in polarized cells, such as neurons, but not in non-polarized neuroblastoma cells." (PMID 33203136, 2020).
tumor (6 papers, 2009 to 2023). "However, no associated tumor was found in any of the published cases associated with anti-septin-5 autoantibodies." (PMID 36997937, 2023).
cancer (5 papers, 2009 to 2024). A tumor composed of atypical neoplastic, often pleomorphic cells that invade other tissues. "The second most recurrently altered TAD boundary (chr22:19600000–19675000) was flanked by active and low-active TADs, and is adjacent to TADs containing the cancer genes SEPTIN5, DGCR8, and HIRA." (PMID 38758740, 2024).
infection (4 papers, 2012 to 2021). The state of being infected such as from the introduction of a foreign agent such as serum, vaccine, antigenic substance or organism. "By tracking actin-binding proteins, septin-5 and autophagosome components, we show that Tpc1 regulates cytoskeletal dynamics and infection-associated autophagy during appressorium-mediated plant penetration." (PMID 28742127, 2017). "The staining intensity was clearly stronger in infected tissues indicating an upregulation of septin 5 protein at the area of infection." (PMID 33801245, 2021). "Apart from this, Septin5 was also significantly up regulated during infection with HPAI H5N1." (PMID 22361110, 2012). "We found that, CRMP2, Septin 5 and SNAP25 genes were significantly up regulated in chicken brain in the time of infection." (PMID 22361110, 2012). "The gene for septin 5, a vesicle and membrane associated protein involved in exocytosis, was among the upregulated genes after infection with HPAI H5N1; infection with NDV did not change the septin 5 expression levels." (PMID 33801245, 2021).
SEPTIN5 also shares sentences with these, for which no sentence is quoted: neurodegenerative disease (5 papers); acute myeloid leukemia (3); Parkinson’s (3); Alzheimer disease (2); diseases of the nervous system (2); psychiatric disorder (2); autism spectrum disorder (1); Bernard-Soulier syndrome (1); bipolar disorder (1); bleeding disorders (1); breast carcinoma (1); breast invasive carcinoma (1); cholangiocarcinoma (1); Cognitive impairment (1); diabetes (1); Dysarthria (1); Encephalopathy (1); epilepsy (1); eye movement disorders (1); fragile X syndrome (1); glioblastoma multiforme (1); head and neck squamous cell carcinoma (1); hematological malignancies (1); infectious viral disease (1); influenza (1); leukemia (1); lung squamous cell carcinoma (1); melanoma (1); mucosal (1); myelodysplastic syndrome (1).
A further 7 diseases each share a sentence with SEPTIN5 in 1 paper.